CCL16 (C-C motif chemokine ligand 16)
Description:
Shows chemotactic activity for lymphocytes and monocytes but not neutrophils. Also shows potent myelosuppressive activity, suppresses proliferation of myeloid progenitor cells. Recombinant SCYA16 shows chemotactic activity for monocytes and THP-1 monocytes, but not for resting lymphocytes and neutrophils. Induces a calcium flux in THP-1 cells that were desensitized by prior expression to RANTES.
Synonyms: HCC-4; LMC; MTN-1; ILINCK; NCC4; SCYA16; NCC-4; SCYL4; LEC; LCC-1; CKb12
Tractability: Antibody: its Gene Ontology location is reachable by antibodies, with high confidence; UniProt places it where antibodies can reach, with medium confidence; UniProt predicts a signal peptide or a membrane-spanning region.
Gene: Protein-coding gene on chromosome 17 (35,976,194 to 35,981,537, reverse strand). Ensembl gene ENSG00000275152.
Subcellular location: Secreted
Pathways (Reactome):
Signal Transduction: Chemokine receptors bind chemokines; G alpha (i) signalling events
Gene Ontology:
Molecular function: chemoattractant activity; protein binding; CCR chemokine receptor binding; chemokine activity
Biological process: antimicrobial humoral immune response mediated by antimicrobial peptide; cell communication; cell-cell signaling; chemokine-mediated signaling pathway; chemotaxis; eosinophil chemotaxis; inflammatory response; positive regulation of cell migration; immune response; positive chemotaxis
Cellular component: extracellular region
Genetic constraint (gnomAD): Loss-of-function variants: 6 observed, 6.71 expected, observed/expected ratio (o/e) 0.89, 90% interval 0.49 to 1.68. That is too few expected variants to judge how well the gene tolerates losing a copy. Missense variants: 130 observed, 141.51 expected, observed/expected ratio (o/e) 0.92, 90% interval 0.8 to 1.06. Synonymous variants: 55 observed, 56.09 expected, observed/expected ratio (o/e) 0.98, 90% interval 0.79 to 1.23.
Homologues: Orthologues: chimpanzee CCL16 (99% identical), macaque CCL16 (85% identical), pig CCL16 (67% identical), dog CCL16 (56% identical), zebrafish ccl35.1 (23% identical), zebrafish ccl35.2 (23% identical). Paralogues in human: CCL14 (31% identical), CCL4 (31% identical), CCL5 (31% identical), CCL8 (31% identical), CCL13 (30% identical), CCL7 (30% identical), CCL3L3 (29% identical), CCL11 (28% identical), CCL21 (28% identical), CCL23 (28% identical), CCL3 (28% identical), CCL4L2 (28% identical), and 14 more.
Diseases named in the same sentence as CCL16 in open-access papers:
CCL16 is named in the same sentence as 44 diseases in open-access papers, as found by Europe PMC text mining. Sharing a sentence is not in itself a finding about the gene and the disease. The quoted sentences say what the papers report.
breast carcinoma (14 papers, 2015 to 2026). "In addition, plasma CCL16 was positively associated with luminal A breast cancer but inversely associated with triple-negative breast cancer." (PMID 36685922, 2022). "To verify the observations in clinical samples, we studied the in vitro CCL16 expression by Western blot analysis of sCCL16 and total CCL16 protein in breast cancer cell lines and normal breast cell lines." (PMID 33500726, 2021). "The results show that CCL16 expression is higher in breast cancer cell lines (especially in MDA-MB-231 and BT549 cell lines) versus normal breast cell lines." (PMID 33500726, 2021). "To gain insight into the importance of CCL16 in the promotion of stemness in breast cancer cells in vivo, we performed xenograft experiments using a limited dilution xenograft assay of MDA-MB-231 cells." (PMID 33500726, 2021). "In the present study, we investigate the role and mechanism of CCL16 in the progression of breast cancer in vitro and in vivo." (PMID 33500726, 2021). "The results show that CCL16 immunostaining is stronger in breast cancer tissue versus normal breast tissue." (PMID 33500726, 2021). "The results show that CCL16 immunostaining is stronger in breast cancer tissue versus adjacent normal breast tissue." (PMID 33500726, 2021). "To further confirm this finding, we investigated CCL16 immunostaining of tissue slides containing 20 pairs of breast cancer tissue and adjacent normal breast tissue." (PMID 33500726, 2021). "This mediates nuclear translocation of β-catenin where it binds to the OCT4 promoter gene (i.e., a stemness gene); therefore, CCL16 plays a role in breast cancer CSC-like identity maintenance." (PMID 33500726, 2021). "In summary, our findings indicate that CCL16 expression is up-regulated by IL10/STAT3 signaling in breast cancer in vitro and in vivo." (PMID 33500726, 2021). "We also observed that CCL16 expression correlates with breast tumor grade and breast cancer progression." (PMID 33500726, 2021). "We next studied IL10 and CCL16 expressions using immunohistochemistry in breast cancer tissues." (PMID 33500726, 2021). "In addition, we measured serum CCL16 (sCCL16) levels in serum from patients with breast cancer and healthy subjects (n = 20)." (PMID 33500726, 2021). "We observed a positive correlation between IL10 and CCL16 immunostaining in breast cancer tissues." (PMID 33500726, 2021). "To test whether CCL16 regulates the stemness of breast cancer cells, we examined the mechanism by which CCL16 regulates CSCs using various experimental approaches." (PMID 33500726, 2021). "However, investigations into CCL16 protein expression in breast cancer tissues have been limited at best." (PMID 33500726, 2021). "Moreover, we confirmed the stronger CCL16 immunostaining in 8 pairs of fresh breast cancer tissue and adjacent normal breast tissue by qRT-PCR and Western blot." (PMID 33500726, 2021). "However, we found that XAV939 reduced β-catenin nuclear translocation and abolished CCL16-mediated breast cancer CSC-like identity maintenance in vitro." (PMID 33500726, 2021). "To investigate the CCL16 expression pattern in human breast cancers, we performed immunohistochemistry using a CCL16-specific antibody in breast cancer tissue microarrays containing 80 biopsies (70 breast cancer tissues and 10 normal breast tissues)." (PMID 33500726, 2021). "Finally, we take the position that CCL16 may serve as a novel therapeutic target in breast cancer treatment." (PMID 33500726, 2021). "We propose that CCL16 could be an effective target for breast cancer therapy." (PMID 33500726, 2021). "Moreover, serum IL10 shows a positive correlation with serum CCL16 in patients with breast cancer." (PMID 33500726, 2021). "CCL16 binds to chemokine receptors (CCR1, CCR5, and CCR8) to activate angiogenesis in vascular endothelium and is related with prognosis in breast cancer and lung cancer." (PMID 36245978, 2022).
breast carcinoma (continued). "In order to confirm the correlation between CCL16 and β-catenin/OCT4, we studied the expression levels of CCL16, β-catenin, and OCT4 using immunohistochemistry in 40 human breast cancer samples." (PMID 33500726, 2021). "In conclusion, we discovered that CCL16 drives stem-cell like properties in MDA-MB-231 and BT549 breast cancer cells in vitro and in a xenograft NOD/SCID mouse model." (PMID 33500726, 2021). "We also studied the correlation between CCL16 and CCR2 using immunohistochemistry in 40 human breast cancer tissues." (PMID 33500726, 2021). "However, the specific role that CCL16 plays in breast cancer remains unclear." (PMID 33500726, 2021). "Having identified the functional and mechanistic roles of CCL16 in CSC-like identity maintenance, we next explored the reason why CCL16 upregulation occurs in breast cancer." (PMID 33500726, 2021). "We found that CCL16 drives cancer cell stemness in MDA-MB-231 and BT549 breast cancer cells in vitro and in a xenograft NOD/SCID mouse model." (PMID 33500726, 2021). "XAV939 (a β-catenin inhibitor) blocks β-catenin nuclear translocation and thereby abates CCL16-mediated breast cancer CSC-like identity maintenance and breast cancer progression." (PMID 33500726, 2021). "CCL16 also activates the angiogenic process in vascular endothelial cells via CCR1 and shows an elevated expression in lymphoid neo-organogenesis of breast cancer." (PMID 33500726, 2021). "Thus, we suggest that CCL16 may serve as an effective target in breast cancer therapy." (PMID 33500726, 2021). "The reduced CCL16 expression abates CCL16-mediated breast cancer CSC-like identity maintenance and breast cancer progression." (PMID 33500726, 2021). "For example, CCL2, CCL5, CXCL8, and CXCL12 can promote breast cancer, while CXCL9, CXCL10, and CCL16 can inhibit breast cancer." (PMID 32253815, 2020). "CCL16 is expressed in STAD, PRAD, and LIHC, which is more obvious in breast cancer." (PMID 36016607, 2022). "Moreover, ICAM3, CCL16, PDE3A, PRTN3, TRAF6, BCAR1, IL-1α, IL-1β, NFκB1, SOX2 and OCT4 decreases the protein expression as indicated by immunofluorescence staining in the ibuprofen-treated MDA-MB-231 breast cancer cells versus the control." (PMID 32528119, 2020).
irritable bowel syndrome (3 papers, 2020 to 2022). Irritable bowel syndrome (IBS) is a chronic functional condition of the lower gastrointestinal (GI) tract characterized by abdominal pain or discomfort and disordered bowel habit (diarrhea, constipation, or fluctuation between the two). "High levels of CCL-16 in serum and plasma are closely correlated with inflammation-related diseases, such as irritable bowel syndrome (IBS) and ulcerative colitis (UC)." (PMID 34686650, 2021). "While an increase in the levels of CCL16 is associated with cardiovascular death in patients with cardiovascular dysfunction and also with irritable bowel syndrome with diarrhea, its role in renal impairment is not clear." (PMID 35723372, 2022). "CCL16 is a pro-inflammatory chemokine that may be involved in the development of diseases such as irritable bowel syndrome." (PMID 32316129, 2020).
lung carcinoma (3 papers, 2021 to 2024). "Furthermore, bioinformatics studies have reported that CCL16 is a prognostic biomarker for triple-negative breast cancer and lung cancer metastasis." (PMID 33500726, 2021). "In addition, CCL16 is a prognostic biomarker that predicts metastasis in both triple-negative breast cancer and lung cancer." (PMID 33500726, 2021).
triple-negative breast carcinoma (3 papers, 2015 to 2022). An invasive breast carcinoma which is negative for expression of estrogen receptor (ER), progesterone receptor (PR), and human epidermal growth factor receptor 2 (HER2). "However, we still found a potential causal association between CCL16 and triple-negative breast cancer." (PMID 36685922, 2022).
COVID-19 (2 papers, 2021 to 2023). A disease caused by infection with severe acute respiratory syndrome coronavirus 2. "Except CCL16, which was higher in controls, all proteins were overexpressed in COVID-19 patients." (PMID 35145507, 2021).
endometriosis (2 papers, 2007 to 2017). The growth of functional endometrial tissue in anatomic sites outside the uterine body. "CCL16 mRNA was elevated in women with endometriosis, and immunoreactive CCL16 was predominantly demonstrated in the endometrium." (PMID 28362325, 2017). "Real-time PCR verified that there were differences in the mRNA encoding CCL16 and CCL21, the two chemokines selected for further study, but that there was considerable heterogeneity in expression in individual endometriosis subjects." (PMID 17506907, 2007). "This study provides novel candidate molecules and suggests a potential local role for CCL16 and CCL21 as mediators contributing to the inflammatory events associated with endometriosis." (PMID 17506907, 2007). "CCL21 mRNA was more abundant than that of CCL16 and was markedly elevated in eutopic glands from one endometriosis patient (mean, 0.61 fg/pg 18S RNA)." (PMID 17506907, 2007). "Overall there was a significant elevation in eutopic endometrial glandular CCL16 expression in women with endometriosis compared to controls (n = 3; P = 0.049)." (PMID 17506907, 2007). "In contrast, in women with endometriosis, eutopic CCL16 and CCL21 mRNA levels were increased in some subjects but with significant patient-to-patient variability." (PMID 17506907, 2007). "In addition to their upregulation in eutopic endometrium from women with endometriosis, examination of CCL16 and CCL21 in ectopic tissues demonstrated a significant increase in protein relative to expression in eutopic tissue derived from the same individual." (PMID 17506907, 2007). "Furthermore, immunoreactive CCL16 was more intensely stained in epithelium in ectopic endometriosis lesions compared with matched eutopic tissue, and there was a similar trend for CCL21." (PMID 17506907, 2007). "In this study, mRNA expression for CCL16 was below the detection limit in the LCM glands from all 3 controls and 1 of the 3 endometriosis patient samples." (PMID 17506907, 2007). "CCL16 and CCL21 mRNA was confirmed as elevated in some women with endometriosis compared to controls on individual samples." (PMID 17506907, 2007). "These combined data clearly show that the expression of CCL16 and CCL21 is disturbed at least in some patients with endometriosis." (PMID 17506907, 2007). "Further, two novel candidate molecules, CCL16 and CCL21, not previously linked to endometriosis have been validated." (PMID 17506907, 2007).
hepatocellular carcinoma (2 papers, 2020 to 2023). A malignant tumor that arises from hepatocytes. "Specifically, in co-culture experiments, CCL16-overexpressing hepatocellular carcinoma cells promoted migration and M2 polarization of macrophages towards tumor cells." (PMID 38274805, 2023). "Chemokine CCL16 (other names: HCC-4, liver expressed chemokine (LEC), liver-specific CC chemokine-1 (LCC-1)) is constitutively expressed in the liver and by hepatoma cells, as well as by monocytes treated with interleukin (IL)-10." (PMID 33182504, 2020). "However, the role of CCL16 in the hepatocellular carcinoma microenvironment remains to be further investigated." (PMID 38274805, 2023).
liver cirrhosis (2 papers, 2022). "It should, however, be noted that in contrast to the well-documented detrimental effect of increased concentration of CCL16 on renal function, low plasma CCL16 was significantly related to hepatic dysfunction in patients with chronic hepatitis B and liver cirrhosis." (PMID 35723372, 2022). "CCL16 could reduce liver cirrhosis by inhibiting the activation of HSCs in mice, suggesting that it may be a marker to predict the occurrence and progression of liver cirrhosis." (PMID 35281057, 2022). "The authors hypothesized that an increased CCL16 might reduce liver cirrhosis through inactivating hepatic stellate cells which, although beneficial in liver cirrhosis, would not be beneficial in attenuating the progression of renal disease." (PMID 35723372, 2022). "However, it is not clear whether this protective action of CCL16 is specific to the liver or applies more generally to the various stages of liver cirrhosis." (PMID 35723372, 2022).
lymph node metastasis (2 papers, 2021 to 2023). "Clinical samples demonstrated a significant association between CCL16 protein expression levels and advanced stage, lymph node metastasis, and distant metastasis." (PMID 38274805, 2023). "In addition, we observed that Cluster of differentiation 40 (CD40, p = 0.017), C–C motif chemokine 16 (CCL16, p = 0.019) and IL-6 (p = 0.021) were highly secreted from PDS MCF7-cultures from patients with lymph node metastasis." (PMID 34090457, 2021).
bladder cancer (1 paper, 2023). "The TCGA bladder cancer dataset revealed a significant correlation between the expression levels of CCL16 and PRPF19 (r=0.166)." (PMID 38022515, 2023). "There exists a potential regulatory relationship between PRPF19 and CCL16, which may contribute to the promotion of stemness in bladder cancer cells." (PMID 38022515, 2023).
bladder tumor (1 paper, 2023). "Hence, it is postulated that PRPF19 potentially modulates the stemness of bladder tumor cells by influencing the expression of the senescence-associated secretory phenotype-associated gene CCL16." (PMID 38022515, 2023).
breast tumors (1 paper, 2021). "In this study, we found overexpression of CCL16 protein in breast tumor tissue using tissue microarrays and in serum using ELISA." (PMID 33500726, 2021). "In this study, we observed that CCL16 (a potential cancer stemness gene) is overexpressed in breast tumors and significantly correlates with clinical progression." (PMID 33500726, 2021).
cyst (1 paper, 2007). A sac-like closed membranous structure that may be empty or contain fluid or amorphous material. "In some ectopic peritoneal lesions, large irregular cyst-like structures were present and strong staining for both CCL16 and CCL21 was apparent in glandular epithelial cells and in secretions within the cyst." (PMID 17506907, 2007).
Hepatitis (1 paper, 2021). Inflammation of the liver. "Blockade of the pathways involved in CPAP-mediated CCL-16 expression or inhibition of the interaction between CCL-16 and its receptors may provide a novel strategy in hepatitis and HCC therapies." (PMID 34686650, 2021). "CCL-16 has been reported to be overexpressed in human hepatocytes and HepG2 cells, and the current studies suggest a potential role of overexpressed CCL-16 in liver inflammation which is important for the development of hepatitis and HCC." (PMID 34686650, 2021).
liver cancer (1 paper, 2023). An epithelial or non-epithelial malignant neoplasm that arises from the liver. "Next, to confirm whether CCL16 expressed by liver cancer cells is associated with macrophage recruitment, we generated HEPG2 cells with CCL16 knockdown and SNU761 cells with CCL16 overexpression." (PMID 38274805, 2023). "Through single-cell data analysis, we identified specific expression of the chemokine CCL16 in liver cancer cells, while its receptor CCR1 was specifically expressed in macrophages." (PMID 38274805, 2023). "Subsequently, we validated the mRNA expressions of CCL16 in several liver cancer cell lines available in our laboratory through qPCR, which were consistent with the database results, with HEPG2 cells showing the highest expression and SNU761 cells showing the lowest expression." (PMID 38274805, 2023). "In order to examine this hypothesis, we initially examined the CCL16 expression in various liver cancer cell lines by utilizing the CCLE database." (PMID 38274805, 2023).
liver diseases (1 paper, 2022). "Although a variety of chemokines have been well studied in various diseases, there is no comprehensive review presenting the roles of all known chemokine ligands of CCR2 (CCL2, CCL7, CCL8, CCL12, CCL13, CCL16, and PSMP) in liver disease, and this review aims to fill this gap." (PMID 35281057, 2022). "However, other ligands of CCR2 have not been thoroughly studied in liver diseases, especially CCL7, CCL8, CCL12, CCL13, CCL16, and PSMP." (PMID 35281057, 2022).
liver fibrosis (1 paper, 2021). "The increased expression of CCL-16 could be used as a biomarker for early prediction of HCC development, and this is not correlated with liver fibrosis." (PMID 34686650, 2021).
mesothelioma (1 paper, 2025). A usually malignant and aggressive neoplasm of the mesothelium which is often associated with exposure to asbestos. "Significantly higher levels of multiple chemokines were expressed in R- vs NR- mesotheliomas, namely CCL5, CCL16, CCL17, CCL19, CCL21, CCL25, and CXCL14 Benajmini-Hochberg adjusted P values < 0.05." (PMID 40691143, 2025).
neuropathic pain (1 paper, 2016). Chronic pain caused by damage to nerve fibers. "Of the 47 investigated proteins, 21 (cathepsin S, CCL2, CCL4, CCL16, CFIII, CXCL5, cystatin B, E-Selectin, Fas/TNFRSF6, follistatin, GDF-15, GH, ICAM1, IL8, KLK5, MMP2, MMP9, P-Selectin, sortilin, TIMP4 and VEGF) were detectable by multiplex SP-PLA in ≥ 95% of the neuropathic pain patient samples." (PMID 26914813, 2016).